VNN1 (vanin 1)
Diseases named in the same sentence as VNN1 in open-access papers (continued):
Sharing a sentence is not in itself a finding about the gene and the disease.
colorectal cancer (6 papers, 2020 to 2025). A primary or metastatic malignant neoplasm that affects the colon or rectum. "VNN1 deficient mice developed resistance to oxidative stress, thus inhibiting intestinal inflammation and reducing the incidence of colorectal cancer." (PMID 36339597, 2022). "Most studies proposed that the expression of VNN1 is upregulated in UC; in addition, stimulating the expression of VNN1 will promote the occurrence of colorectal carcinoma." (PMID 35959356, 2022). "In colorectal cancer, vanin-1 influences glutathione levels, impacting carcinogenesis." (PMID 39596804, 2024). "In colorectal cancer, GPRC5A promotes tumor formation by regulating NF-κB-mediated Vanin-1 expression and oxidative stress." (PMID 38634049, 2024).
Insulin resistance (6 papers, 2016 to 2025). Increased resistance towards insulin, that is, diminished effectiveness of insulin in reducing blood glucose levels. "Interestingly, in models of vanin-1 deficiency, mice exhibited worsened insulin resistance and glucose tolerance." (PMID 40954177, 2025). "In a diabetic model, increased Vnn1 induced a reduction in Akt phosphorylation, which might be associated with insulin resistance." (PMID 32139393, 2020). "Specifically, knocking down vanin-1 in the liver alleviated insulin resistance and impaired glucose tolerance." (PMID 40954177, 2025). "More importantly, Vanin‐1 overexpression also improved glucose intolerance and insulin resistance in these animals." (PMID 32714762, 2020). "Surprisingly, our study found that VNN1 expression was increased in the pancreas of OVX mice, which may be associated with insulin resistance due to postmenopause." (PMID 38966541, 2024). "Although we observed a strong upregulation of hepatic Vnn1 expression and plasma vanin activity in obese, insulin resistant mice and rats, our results suggest that vanin-1 only plays a minor role in the pathophysiology of insulin resistance." (PMID 26932716, 2016). "Another explanation for the differences observed in RR6-treated rats and Vnn1−/− mice could possibly be that not vanin activity, but the presence of vanin-1 protein may be (mildly) involved in the development of insulin resistance." (PMID 26932716, 2016).
colon carcinoma (5 papers, 2014 to 2022). "Studies have shown that GPRC5A is a potential biomarker for colon cancer and promotes the occurrence of tumors in colitis-associated cancers by stimulating vanin-1 expression and oxidative stress." (PMID 33505587, 2021). "However, vanin-1 deficiency may also reduce colon cancer development by down-regulating several mediators of inflammation in intestinal epithelial cells that promote colorectal carcinogenesis and that are overexpressed in tumors, as COX-2, iNOS and MMP9." (PMID 28448444, 2017). "However, vanin-1 deficiency may also limit the development of colon cancer by down-regulating several mediators of inflammation in intestinal epithelial cells that promote colorectal carcinogenesis and are overexpressed in tumor as COX-2, iNOS and MMP9." (PMID 28448444, 2017). "Vanin-1−/− mice showed protective effects against a variety of phenotypes, such as oxidative stress, intestinal inflammation, and colon cancer, mostly due to higher glutathione storage to maintain a more reducing environment." (PMID 25233454, 2014). "In colonic tumors, lack of vanin-1 is associated to higher levels of PPAR and to a reduction in IL-6 production and STAT3 activation, whose levels correlate with tumor size." (PMID 28448444, 2017). "In colonic tumors, lack of vanin-1 is associated to higher levels of PPARg and to a reduction in IL-6 production and STAT3 activation." (PMID 28448444, 2017). "Our mining of a microarray dataset of serrated colon carcinoma specimens determined that peptidase inhibitor 3 (PI3), vanin 1 (VNN1) and annexin 10 (ANXA10) are more highly expressed in such cancers as compared to conventional colon carcinomas." (PMID 24533081, 2014).
dyslipidemia (5 papers, 2020 to 2025). "Furthermore, Vnn1 is expressed by the centrilobular hepatocytes and is involved in lipid and xenobiotic metabolism, whereas Pex11a (peroxisomal biogenesis factor 11 alpha) is involved in peroxisome maintenance and proliferation associated with dyslipidemia." (PMID 35935858, 2022). "In the context of T2DM and dyslipidemia, VNN1 upregulation likely exacerbates oxidative stress and inflammatory cascades, contributing to the systemic metabolic dysregulation observed across the groups." (PMID 40458179, 2025). "Therefore, studies in fasted and HFD‐fed mice in the Vanin‐1 deficient background suggest that Vanin‐1 is a bona fide regulator of lipolysis in the abdominal adipose tissues, and Vanin‐1 deficiency blunts lipolysis, leading to the aggravated metabolic syndromes in HFD‐fed mice." (PMID 32714762, 2020). "TGFB1I1, VNN1, HLADRB4, and CXCL8 genes were differentially expressed in lymphocytes and monocytes of subjects with poorly controlled diabetes mellitus, dyslipidemia, and periodontitis in comparison with controls." (PMID 36233348, 2022).
Hepatic steatosis (5 papers, 2016 to 2024). Steatosis is a term used to denote lipid accumulation within hepatocytes. "PPAR-α contributes to liver homeostasis by limiting steatosis; however, the association of vanin 1 with hepatic steatosis is somewhat ambiguous." (PMID 31404995, 2019). "Animal experiments demonstrated that hepatic VNN1 expression was induced in db/db and diet-induced obese mice exhibiting severe hepatic steatosis and that liver-specific knockdown of VNN1 ameliorated hepatic steatosis in these animal models." (PMID 38966541, 2024). "However, we show that hepatic steatosis as reflected by hepatic TG levels and HE staining was not affected by vanin-1 deficiency in LFD- or HFD-fed mice." (PMID 26932716, 2016). "In addition, when rats were treated with the vanin 1 inhibitor RR6 for four days and subsequently fasted for 24 h, they showed an increased liver weight, indicating increased hepatic steatosis." (PMID 31404995, 2019). "The first objective of the current study was to examine whether absence of vanin-1 or inhibition of vanin activity, would affect hepatic steatosis in obese animal models." (PMID 26932716, 2016).
periodontitis (5 papers, 2020 to 2025). An acute or chronic inflammatory process that affects the tissues that surround and support the teeth. "A recent transcriptomic analysis of circulating lymphocytes and monocytes indicated that the VNN1 gene was upregulated in patients suffering from type II diabetes mellitus, periodontitis, and dyslipidemia simultaneously in contrast with normal individuals." (PMID 36527111, 2022). "Results suggested that the Vanins were upregulated in the gingival tissues from patients with periodontitis when compared with periodontal healthy individuals, among which two members, VNN1 and VNN2 were elevated on both the genetic and protein levels." (PMID 36527111, 2022). "The link between periodontitis, oxygen stress and VNN1 may provide clues for further exploration of the pathological process of periodontitis." (PMID 36527111, 2022). "The findings revealed that the expression levels of VNN1 and VNN2 were significantly upregulated in the periodontitis cohort." (PMID 38491529, 2024). "The validation analyses using RT-qPCR showed that four genes were differentially expressed in subjects with poorly controlled T2DM plus DL plus periodontitis compared to HS (TGFB1I1, VNN1, HLADRB4 and CXCL8)." (PMID 36233348, 2022). "Generally speaking, expression levels of VNN1, VNN2 and VNN3 were higher in gingival tissues from periodontitis patients at the genetic level in both RT-qPCR and GEO dataset analysis." (PMID 36527111, 2022). "The results supported that VNN1 and VNN2 were enriched in gingival tissues affected by periodontitis, especially in the part of connective tissues." (PMID 36527111, 2022). "Assessment using western blot and immunohistochemistry presented significant upregulations of VNN1 and VNN2 in periodontitis (p < 0.05)." (PMID 36527111, 2022). "Importantly, one gene, VNN1 (Vanin-1), was consistently overexpressed across all groups, with log2 fold changes of 1.59, 1.53, 1.33, and 1.38 in DLP-H, T2DMpoorly-DLP-H, T2DMwell-DLP-H, and Periodontitis-H, respectively." (PMID 40458179, 2025).
diabetic nephropathy (4 papers, 2015 to 2025). "Previous studies have identified VNN1 as a biomarker for diabetic nephropathy and as a therapeutic target for reducing oxidative damage in metabolic disorders." (PMID 40458179, 2025). "Recent research discovered that streptozotocin-induced diabetic nephropathy in rats was associated with higher protein content of tubular vanin-1, and urine vanin-1 was found in diabetic nephropathy patients." (PMID 36648873, 2022). "Recently, we and others have demonstrated that vanin-1 is an AKI biomarker with good diagnostic value in various kidney diseases, such as diabetic nephropathy and drug-induced renal tubular injury." (PMID 30791405, 2019).
kidney injury (4 papers, 2018 to 2024). Trauma to the kidney. "For example, urinary and serum vanin-1 were upregulated in inflammation induced by ethylene glycol-induced kidney injury." (PMID 36718335, 2022). "Although novel, sensitive biomarkers for KI have emerged quickly, such as IL6, cystatin C, kidney injury molecule-1, NGAL, urine vanin-1, and liver fatty acid-binding protein, BUN and Scr are still the most utilized biomarkers to assess kidney injuries in experimental animal models." (PMID 32630021, 2020).
pancreatic cancer (4 papers, 2020 to 2025). "VNN1 has shown its involvement in inflammation and lipid metabolism as well as a potential biomarker for pancreatic cancer-associated new-onset diabetes." (PMID 38029961, 2024). "Another study found that pancreatic cancer cells overexpressing VNN1 aggravate paraneoplastic islet dysfunction by causing oxidative stress and β-cell dedifferentiation." (PMID 38022651, 2023). "Pancreatic cancer cells overexpressing Vanin-1 (VNN1) secrete cysteamine and exosomes, inducing oxidative stress and thereby exacerbating the dysfunction of paraneoplastic islets." (PMID 40534881, 2025).
acute kidney injury (3 papers, 2019 to 2026). Sudden and sustained deterioration of the kidney function characterized by decreased glomerular filtration rate, increased serum creatinine or oliguria. "Increased levels of urinary vanin-1 associated with acute kidney injury were observed in patients with upper urinary tract obstruction and decreased at 4 weeks after intervention." (PMID 36718335, 2022). "Pantetheinase and vanin-1 also play a role in the inflammatory process that leads to acute kidney injury." (PMID 36718335, 2022).
liver fibrosis (3 papers, 2020 to 2025). "Notably, Angiogenic factor with G patch and FHA domains 1 (AGGF1) regulates liver fibrosis and may contribute to Metabolic dysfunction-associated steatohepatitis (MASH) pathogenesis just like Vanin-1 (VNN1) and Suv39h2, two histone methyltransferases." (PMID 41272759, 2025).
sarcoma (3 papers, 2018 to 2024). A usually aggressive malignant neoplasm of the soft tissue or bone. "VNN1 expression in sarcomas is associated with better prognosis and immune infiltration." (PMID 37833072, 2023). "Therefore, we tested whether VNN1 expression was associated with immune signatures in sarcomas and whether enhancing VitB5 levels via Pant administration could enhance mitochondrial metabolism and anti-tumor immunity in a mouse model." (PMID 37833072, 2023). "Accordingly, VNN1 expression tends to be lost in advanced sarcomas and a in a limited set of human sarcomas, VNN1 transcript levels are associated with improved metastasis-free survival (MFS)." (PMID 37833072, 2023). "Using an aggressive sarcoma cell line that lacks Vnn1 expression, we showed that the administration of pantethine, a vitamin B5 precursor, attenuates tumor growth in immunocompetent but not nude mice." (PMID 37833072, 2023). "Of the three cohorts of mice tested, the few other sarcomas were only found in the liver or spleen in which Vnn1 can be expressed by various cell types." (PMID 30456364, 2018). "We reasoned that strategies that exploit the immune-boosting effect of the Vnn1 pathway observed in autoimmune or infectious models might enhance the development of anti-sarcoma immunity." (PMID 37833072, 2023). "In this study, we provide the first experimental evidence that induction of Vnn1 pantetheinase activity in a mouse sarcoma model contributes to the regeneration of mitochondrial CoA stores through the production of pantothenate from PantSH, leading to enhanced mitochondrial fitness." (PMID 30456364, 2018). "Therefore, we tested whether VNN1 expression in human sarcomas might be correlated with enhanced survival and/or development of antitumor responses." (PMID 37833072, 2023). "STS developing on the Vnn1−/− background were mostly grade II and III sarcomas." (PMID 30456364, 2018). "As a surrogate mouse model of complex sarcomas, we implanted the Vnn1negative MCA 205 (MCA) sarcoma cell line in immunocompetent mice to test whether systemic administration of Pant would compensate for the lack of Vnn1 in the tumor mass." (PMID 37833072, 2023).
steatosis (3 papers, 2016 to 2019). Increased lipid within the cytoplasm of cells. "This would imply a causal role for vanin 1 in the progression of steatosis." (PMID 31404995, 2019). "Recent studies, however, suggest that acute inhibition of Vanin-1 activity in Zucker Diabetic Fatty rats did not change the degree of steatosis nor did it affect insulin sensitivity or glucose production." (PMID 27667588, 2016). "AlthoughVanin-1 plays a role in hepatic fatty acid oxidation, and that deviation to either side of normal may lead to steatosis, the contribution of Vanin-1 to the promotion of steatosis and insulin sensitivity in non-laboratory models is less clear." (PMID 27667588, 2016).
acute pancreatitis (2 papers, 2021 to 2022). An acute inflammatory process that leads to necrosis of the pancreatic parenchyma. "In acute pancreatitis, upregulation of S100A9 induces cell injury and inflammatory response through activating NLRP3 via targeting VNN1-mediated ROS release." (PMID 36527111, 2022).
breast carcinoma (2 papers, 2023 to 2024). "In this study, we used a breast cancer model to examine the effects of radiation alone or in combination with estrogens on the expression of genes linked to cell motility, such as ADAM12, CYR61, FLRT2, SLIT2, VNN1, MYLK, MAP1B, and TUBA1A." (PMID 39596804, 2024). "Bioinformatic analysis indicated that FLERT2, SLIT2, VNN1, MAP1B, MYLK, and TUBA1A gene expressions were found to be higher in normal tissue than in tumor tissue of breast cancer patients." (PMID 39596804, 2024). "According to a bioinformatic study, the expression of the genes FLRT2, SLIT2, VNN1, MAP1B, MYLK, and TUBA1A was found to be higher in normal tissue than in malignant tissue in patients with breast cancer." (PMID 39596804, 2024). "On the other hand, the VNN1 and ESR2 genes were positively correlated in Basal and Luminal A breast cancer patients." (PMID 39596804, 2024).
hepatic diseases (2 papers, 2019 to 2025). "Thus, vanin 1 forms an important link between lipid accumulation and hepatic diseases, such as fibrosis." (PMID 31404995, 2019). "Thus, using serum vanin 1 as a biomarker may be of interest to monitor PPAR-α activity in liver disease." (PMID 31404995, 2019).
hydronephrosis (2 papers, 2018 to 2019). Collection of urine in the renal pelvis that results in dilatation of the renal pelvis and calyces. "Vanin-1 is associated with oxidative stress, and therefore, it is possible that urinary vanin-1 levels are also associated with hydronephrosis." (PMID 30332759, 2018). "Again, urinary vanin 1 was marked as a promising candidate biomarker for renal tubular injury, in this case due to hydronephrosis." (PMID 31404995, 2019). "Miyagawa and coworkers analyzed human vanin 1 in samples collected from 28 hydronephrosis cases." (PMID 31404995, 2019). "Therefore, clinical studies are needed to confirm urinary vanin-1 levels in patients with hydronephrosis." (PMID 30332759, 2018). "Considering that obstructive nephropathy in humans is always due to incomplete obstruction, our findings suggest that urinary vanin-1 may be a useful biomarker for hydronephrosis." (PMID 30332759, 2018). "Therefore, urinary vanin-1 may be a potential biomarker of the onset of EMT during the progression of hydronephrosis." (PMID 30332759, 2018). "In this study, we examined whether vanin-1 could be a potential biomarker for hydronephrosis." (PMID 30332759, 2018). "Urinary vanin-1 may serve as a candidate biomarker of renal tubular injury due to hydronephrosis." (PMID 30332759, 2018). "Therefore, the presence of vanin-1 in the renal pelvic urine may reflect renal tubular injury due to hydronephrosis." (PMID 30332759, 2018). "Moreover, they demonstrated that vanin 1 and N-acetyl-β-d-glucosaminidase (NAG) were useful factors to predict hydronephrosis." (PMID 31404995, 2019).
Hyperglycemia (2 papers, 2022). An increased concentration of glucose in the blood. "Recent study elucidated the role of Vnn1 in overactivation of gluconeogenesis, contributing to hyperglycemia, and our study also supports that Vnn1 may be a therapeutic target for NAFLD and associated glucose dysregulation." (PMID 35406736, 2022). "In addition, consistent with our results, some studies reported blood levels of VNN1 were increased in diabetic patients, and VNN1 increased the expression of gluconeogenic genes and hepatic glucose output, which led to hyperglycemia in a diabetic mice model." (PMID 36463101, 2022).
kidney damage (2 papers, 2021 to 2022). "Relevant studies have testified that urinary VNN1 distinctly ascends in patients with nephropathy, implying that urinary VNN1 is able to be employed as a biomarker of renal tubular injury." (PMID 36159576, 2022). "As markers of kidney damage, relative gene expression of Kim1, Ngal and Vnn1 were measured." (PMID 34544493, 2021).
malaria (2 papers, 2016 to 2019). Malaria is a serious and sometimes fatal disease caused by a parasite that commonly infects a certain type of mosquito which feeds on humans. "In a mouse model of infection with P. chabaudi, it was reported that a loss of function in the enzyme pantetheinase (Vnn1/Vnn3) in mouse strain AcB61 causes susceptibility to blood-stage malaria." (PMID 27150250, 2016). "Additionally, vanin 1 also plays a role in malaria susceptibility, psoriasis, carcinogenesis, cardiovascular disease, pediatric immune thrombocytopenia, and systemic sclerosis." (PMID 31404995, 2019).
metabolic dysfunction-associated steatohepatitis (2 papers, 2023 to 2025). Metabolic dysfunction-associated steatohepatitis (MASH, formerly known as nonalcoholic steatohepatitis or NASH) is a type of fatty liver disease. "Serum levels of Vanin-1 have been associated with hepatic lipoplasia and have been considered as a non-invasive inflammatory marker for non-alcoholic steatohepatitis." (PMID 38156278, 2023).